BATF3 (basic leucine zipper ATF-like transcription factor 3)
Diseases named in the same sentence as BATF3 in open-access papers (continued):
Sharing a sentence is not in itself a finding about the gene and the disease.
tumor (continued). "Thus, expression of FGL2 in tumor cells prevents T cell priming by reducing the development of Batf3-dependent CD103+ DCs." (PMID 30683885, 2019). "In this case, the tumor thrombus showed evidence of a T cell-inflamed tumor microenvironment with co-localization of Batf3+ dendritic cells and CD8+ T cells and patchy expression of PD-L1, whereas the immunotherapy-resistant primary renal tumor showed T cell exclusion without PD-L1 expression." (PMID 30857555, 2019). "We further proved that ß-lap induced ICD and activated innate sensing via an HMGB1/TLR4 pathway and upregulated the type I IFNs signaling in the tumor microenvironment, resulting in the promotion of Batf3 DCs to cross-prime T cells and activate of antitumoral adaptive immune response." (PMID 31324798, 2019). "This may result in tumor antigen release and crosspresentation by professional antigen-presenting cells including BATF-3 dependent c-DC1." (PMID 31046839, 2019). "To determine if the reduction in cDC1 differentiation potential could impact tumor immunity and tumor progression, we measured the ability of progenitors isolated from tumor-bearing or tumor-free mice to control tumor growth in BATF3−/− mice." (PMID 29593283, 2018). "Interestingly, multiple smaller fractions of radiation (8 Gy*3) did not induce higher levels of Trex1, rather it induced more IFN-β production and activation of Batf3-dependent DCs, leading to enhanced anti-tumor T cells responses." (PMID 30692991, 2018). "Interestingly, we found that CD11c+ cells, and specifically Batf3-CD11c+ cells, must be present in the tumor before the beginning of anti-PD-L1 treatment for therapeutic efficacy of anti-PD-L1." (PMID 30400822, 2018). "The proportion of BATF3+ cells per 1000 tumor cells ranged from 0 to 6.32 with an average of 0.68." (PMID 30400835, 2018). "Indeed, Batf3−/− mice exhibit an impaired ability to cross-prime cytotoxic T lymphocytes against tumor antigens." (PMID 30115069, 2018). "We further examined the expression of BATF3 and Ki67 in the subcutaneous tumor samples." (PMID 29661228, 2018). "In the current work, we examined whether Batf3+ DCs are also required at a third level, during the effector phase of the anti-tumor immune response upon treatment with PD-1/PD-L1 blockade." (PMID 30400822, 2018). "Therefore, we established a tumor mouse model to illuminate the transformation potency of BATF3 in mature lymphocytes." (PMID 29662618, 2018). "Moreover, Batf3-dependent DCs are crucial for reactivation of circulating CD8+ T-cell memory for anti-tumour immunity." (PMID 28714465, 2017). "Moreover, Batf3-dependent dendritic cells are essential for reactivation of circulating memory anti-tumour response." (PMID 28714465, 2017). "Thus, tumor-derived prostanoids impair accumulation of Batf3-dependent CD103+ DCs within tumors and suppress their activation, including IL-12-producing activity." (PMID 26343581, 2015). "Within the DC compartment, CD8α+ DCs were required to respond to type I IFN and to prime anti-tumor T cell responses in a pre-clinical melanoma model, as Batf3−/− mice, in which CD8α+ DCs fail to develop, generate very poor spontaneous anti-tumor T cell responses." (PMID 25914882, 2015). "Meanwhile, we also constructed Batf3–/– bone marrow chimeric mice, as the development of CD103+ cDC1 was impaired in transcription factor BATF3 deficient mice, and we observed that the antitumor effect of SUP3 also diminished, and the tumor continued to grow in those chimeric mice." (PMID 41291775, 2025). "Therefore, Batf3−/− mice were defective in cross‐presentation of tumor cell antigens." (PMID 37127892, 2023). "Other factors may also contribute to the ability of Alb-IFNβ to control tumor in addition to Batf3." (PMID 35459734, 2022). "Therefore, it is not likely that the impaired induction of anti-tumor CD8+ T cells observed in Batf3−/− mice in our study is caused by T cell-intrinsic Batf3-deficiency, but rather the lack of cDC1-mediated cross-priming." (PMID 36418317, 2022).
tumor (continued). "Thus, the present study further demonstrated that silencing of STEDB1 could dramatically downregulate the expression of PD-L1, thereby promoting T cell cytotoxicity to tumor cells via the FOSB/miR-22/BATF3 axis." (PMID 35497876, 2022). "Indeed, Batf3-lineage DCs migrate to the draining lymph node to mediate T cell cross-priming, while another subset remains in the tumor site to produce CXCR3 ligands CXCL9 and CXCL10 (CXCL11 in humans) used to recruit CD8+ effector T cells back to the target tissue." (PMID 35096624, 2021). "Additional experiments performed in Batf3−/− knockout mice deficient for both CD103+ and CD8α+ DCs29, 43 revealed an absence of the WT1 vaccine-mediated protective responses, stressing the need for CD103+ DCs at the tumor site for induction of antitumor protective immune responses." (PMID 31384667, 2019). "Consistent with our data showing that antigen presentation by the injected APCs was not necessary for tritherapy efficacy, a recent study highlights the ability of Batf3-dependent-DCs to lead to tumor rejection by methods other than cross-presentation, which may play a role in the tritherapy." (PMID 31747946, 2019). "However, there are a few conflicting reports showing that BATF3 might play a positive regulatory role in other tumor cells." (PMID 29661228, 2018). "Release of tumour neo-antigens and epitope spreading following OV-induced necrosis and pyroptosis of cancer cells leads to the recruitment of scavenging macrophages and Batf3+ dendritic cells, enhanced antigen presentation and subsequent activation of antigen-specific CD4+ and CD8+ T-cells." (PMID 29157300, 2017). "Here we show that Batf3-dependent DCs are needed for effective reactivation of Tcm cells to promote anti-tumour immunity, which further supports the crucial role of this DC subset in tumour immunology and immunotherapy, not only for the primary response, but also for the memory response." (PMID 28714465, 2017). "Their dual activity in cross-priming anti-tumor CTL within lymph nodes and restimulating CTL within tumors probably contributes to the general Batf3-dependence of anti-tumor immunity that has been observed in mice and to the suppression of anti-tumor immunity by PGE2 that we observe here." (PMID 26343581, 2015). "MLKL-mRNA therapy induces tumor neoantigen-specific T cell responses, which are dependent on type I IFN signaling and Batf3+ DCs." (PMID 41235238, 2025). "In tumor models, Tim3 on BATF3+CD103+ cDC1s suppresses the production of CXCL9, a chemokine critical for the recruitment of effector CD8+ T cells to the tumor microenvironment, and blockade of Tim3 enhances CXCL9 production and improves antitumor immunity." (PMID 41177809, 2025). "Serum HMGB1 levels reflect tumor cell lysis and ICD-driven DC activation, whereas CXCL9/CXCL10 gradients predict Batf3-dependent CD103+ DC migration and T-cell priming." (PMID 40989107, 2025). "Together, these results suggest that Batf3, TI-IFN signaling, and pDCs are all likely important in Alb-Flt3L–mediated tumor control to varying degrees." (PMID 37917174, 2024). "Overexpression of BATF3 suppressed CAR-T cell exhaustion and enhanced in vivo tumour control in an orthotopic breast cancer model." (PMID 39399500, 2024). "Here, we developed an approach to reprogram tumor cells in vivo by adenoviral delivery of the transcription factors PU.1, IRF8, and BATF3, which enabled them to present antigens as type 1 conventional dendritic cells." (PMID 39236156, 2024). "Anti-PD-1 efficacy is favoured by a T cell-inflamed TME and depends on interactions between Batf3+ DCs and CD8+ T cells within tumor sites." (PMID 37507765, 2023). "In contrast, radiation given in fractionated doses below the dose threshold for Trex1 induction stimulates dying tumor cells to release IFN-β cytokine, which recruits Batf3-dependent DCs and activates anti-tumor CD8+ T cells." (PMID 36993986, 2023).
tumor (continued). "Activation of the TLR3 pathway was essential for the anti-tumor effects of poly (I:C), while TLR3+ Batf3 DCs and CD8+ T cells were indispensable for the therapeutic efficacy of poly (I:C)." (PMID 37112730, 2023). "BATF3 OE markedly enhanced the potency of CD8+ CAR T cells in both in vitro and in vivo tumor models." (PMID 37945901, 2023). "In the BATF3−/− tumor-bearing mice, we showed that CD103 + DCs were required to suppress tumor growth and establish antigen-specific protection against tumor rechallenge in combination therapy." (PMID 35794399, 2023). "BATF3- and CXCR1-DCs secrete CD141, which primes CD8+ T cells for anti-tumor activity and generates CXCL10 to recruit specific CD8+ T cells." (PMID 35205408, 2022). "For optimal tumor control, it has been found that IL12 exerted from Batf3 DCs is the premise for effective NK cell function and production of IFNγ." (PMID 35626062, 2022). "To test the role of cDC1s on tumor-specific T cell priming in PDA, we orthotopically implanted nAg+ tumor cells into the pancreas of Batf3+/+ or Batf3–/– mice, which lack cDC1s." (PMID 35393950, 2022). "By contrast, Batf3-DCs are indispensable for cross-priming of CD8+ T cells and generating de novo anti-tumor T cell responses, therefore, expanding intratumoral DCs is a rational alternative approach to augment oncolytic virotherapy." (PMID 36418317, 2022). "The presence of Batf3 DCs, CXCL9 and CXCL10 in the tumor microenvironment independently correlated with T cell infiltration." (PMID 35626062, 2022). "To identify the non-cDC1 antigen-presenting cell (APC) that primes tumor-specific CD8+ T cells, we depleted various immune cells in Batf3–/– mice prior to orthotopic tumor implantation and αCD40." (PMID 35393950, 2022). "Batf3 dependent CD8+CD103+ DC1 cells, present in the microenvironment of tumors, cross-present tumor antigens to CD8+ T cells in the regional lymph nodes, and are required to initiate an immune response to the tumor." (PMID 34777358, 2021). "A comprehensive analysis of the immune microenvironment revealed an expected increase in the ratio of CD4/CD8 tumor-infiltrating T cells, with the frequency of CD4+ cells more than doubling in the Batf3–/– mice." (PMID 34283809, 2021). "While WT mice showed delayed tumor growth on DNGR-1 blockade, this protection was lost in Batf3–/– mice." (PMID 33980589, 2021). "Despite a general loss of cross-presentation in Batf3–/– mice, cytotoxic T cells could still actively contribute to tumor surveillance through activation by nonclassical cross-presenting DCs and classical DC1s generated by Irf8 compensating for Batf3 deficiency." (PMID 34283809, 2021). "To assess the functional relevance of cross-presenting cDC1 in IL-32–induced tumor control, we examined the effects of IL-32 treatment in B16F10 tumors inoculated in Batf3–/– mice according to the established treatment regimen." (PMID 32841222, 2020). "We show here that BATF3-dependent CD103+ DCs are not only required for therapy success but also for the spontaneous control of tumor growth." (PMID 31188899, 2019). "Murine syngeneic tumor lines expressing SIY were categorized as ‘progressor’ or ‘regressor,’ and implanted in wild-type, Rag2-/-, Batf3-/-, Clec9aGFP/GFP, and CD11c-DTR bone marrow (BM) chimera mice." (PMID 30400822, 2018). "Further, we analyzed IRF8 target gene expression in GMPs, MDPs, and CDPs and found that, relative to controls, tumor-bearing mice had decreased mRNA expression of multiple MHC molecules, as well as TapBP, Tap2, Batf3, and Pml." (PMID 29593283, 2018). "Mechanistically, we found that Batf3-dependent DCs and type I IFN signaling were vital to raise tumor-specific T cell responses upon MLKL-mRNA treatment." (PMID 30143632, 2018).
tumor (continued). "Importantly, Ptgs1/Ptgs2−/− tumors were able to grow in Rag1−/−, Tap1−/−, and Batf3−/− hosts, indicating that prostanoid deficiency did not impair tumor formation in a cell-intrinsic fashion but rather acted to prevent CD8α+/CD103+ DC-dependent rejection mediated by CD8+ T lymphocytes." (PMID 26343581, 2015). "Using these mice as tumor-bearing hosts, we observed that therapeutic antitumor immunity elicited by DCIL-15-based DNA vaccines required host Batf3+ DC subsets in both the GL26 and 4T1.2-Neu models." (PMID 25941586, 2014). "Only when both cDC1s and cross-dressed inflammatory monocytes were absent (B2m KO tumours engrafted into Rag2–/–Batf3–/– mice) did T cells fail to become restimulated." (PMID 39604727, 2025). "Notably, when NTT cells were injected into Rag2–/–Batf3–/– mice, which lack functional cDC1s, and ACT was performed, T cells still infiltrated, expanded and controlled NTT tumours." (PMID 39604727, 2025). "Triggers tumor-specific T-cell responses via type I IFN and Batf3+ DCs." (PMID 41235238, 2025). "The discrepancy between the recent and earlier studies is likely due to XCR-1, but not Batf3 or CD11c, being specifically expressed by cDC1s; Baft3 and CD11c expression by certain non-cDC1 cells likely impacts anti-tumor immunity." (PMID 40227734, 2025). "This may be due to tumor heterogeneity, specific neutrophil gene phenotypes, and reduced production of key components of antitumor immunity, including IL12, BATF3-dependent DCs, IFNɣ, and the CXCR3 chemokine receptor." (PMID 39132507, 2024). "Tumor size was monitored, revealing that Batf3–/– mice treated with Alb-Flt3L plus cisplatin failed to control tumors, which grew significantly faster than those of WT controls." (PMID 37917174, 2024). "The reason why the constitutive absence of CD11chi DCs in CD11c:DTA mice or cDC1 in Batf3-deficient mice leads to the enhanced progression of tumor may be due to the failure of the establishment of the tumor immunosurveillance associated with the occurrence of anti-tumor-specific Teff cells." (PMID 39206204, 2024). "Tumor antigen-specific T-cell responses were characterized by performing in vivo T-cell proliferation assays and the contribution of conventional type 1 DC (cDC1) to T-cell immunity during tumor-targeted therapy was assessed using Batf3−/− mice lacking cDC1." (PMID 38631706, 2024). "Without Batf3, these DCs cannot develop, which limits downstream T cell activation, and ultimately ablates tumor control." (PMID 37917174, 2024). "This suggests that moDCs and their cross-presentation are not affected in Batf3-/- mice and are insufficient for tumor rejection." (PMID 38903502, 2024). "Metastases with low UMIS (versus high UMIS) had a paucity of TIL and were composed of tumor cells with higher beta-catenin transcript expression (CTNNB1), which has been described as a transcriptional repressor of BATF3-lineage dendritic cell recruitment of CD8+ T cells." (PMID 38627362, 2024). "Nevertheless, the increased population of CD8+ T cells observed in IL-33-treated Batf3−/− mice was not effective enough to suppress tumor growth in Batf3−/− TB mice, as previously reported." (PMID 37246159, 2023). "Analysis conducted at day 20 after tumor cell inoculation revealed that IV BCG did not reduce B16-F10 lung metastases in Batf3−/− mice, in contrast to WT mice, which correlated with a lower infiltration of CD8+ T cells in the lungs." (PMID 37794033, 2023). "In control and BATF3 OE cells, we detected equivalent proportions of CD8+ T cells within the tumor and circulating in peripheral blood, indicating that BATF3 OE was not improving tumor control by merely increasing T cell proliferation or tumor trafficking." (PMID 37945901, 2023). "In the BATF3−/− mouse model, the anti-tumor effect of RT plus anti-TIGIT combination therapy was absent." (PMID 35794399, 2023).
tumor (continued). "The treatment regimen resulted in a significant induction and activation of Batf3-dependent conventional type 1 DCs and an increased frequency of tumor-specific CD8+ T cells in primary and distant non-irradiated tumors." (PMID 37112730, 2023). "IL-33-mediated tumor suppression did not occur in Batf3−/− mice, indicating that conventional type 1 dendritic cells (cDC1s) play a key role in IL-33-mediated antitumor immunity." (PMID 37246159, 2023). "Consequently, as a logical next step, the anti‐tumor efficacy of intratumoral NK and anti‐NKG2A/Qa‐1b therapy was evaluated in BATF3−/− mice which are devoid of cDC1 cells." (PMID 37782273, 2023). "Moreover, BATF3 enhanced the potency of CAR T cells in both in vitro and in vivo tumor models and programmed a transcriptional profile that correlates with positive clinical response to adoptive T cell therapy." (PMID 37945901, 2023). "Induced c-Myb expression did not affect tumor growth in Batf3−/− mice, indicating that tumor-derived antigens cross-presented by DCs were required for effective T-cell control of tumor progression." (PMID 37478172, 2023). "The anti-tumor effect of combination therapy was abrogated when CD8 + T cells were not present, with tumor control being similar to that in the BATF3−/− group." (PMID 35794399, 2023). "CB-specific T cells primed in wild-type mice and transferred into tumor-bearing Batf3–/– mice did not acquire Foxp3 or the Klrg1+Lag3+ subset." (PMID 35393950, 2022). "Indeed, IL-33 expression correlated strongly with CD8A and granzyme B as well as genes like BATF3, IRF8, THBD, CLEC9, and XCR1 that are required for tumor antigen cross-presentation functionality of CD103+ dendritic cells (DCs)." (PMID 36256464, 2022). "Prior studies suggest Batf3 is required for antitumor activity when CD40 agonist is used in combination with chemotherapy and immune checkpoint blockade, for the most part in subcutaneous tumor models." (PMID 35393950, 2022). "Tumor studies with these Irf8 + 32–/– mice firmly established that cDC1 itself, not Batf3 acting in other cells, is required for the rejection of tumors." (PMID 34480145, 2022). "To determine if cDC1s influenced these T cell subsets, we used the conditional cDC1 depletion approach because tumor-specific T cells are not detectable in Batf3–/– mice." (PMID 35393950, 2022). "Subsequently, we analyzed SQLE expression and its association with biomarkers of MHC (B2M, HLA-B, HLA-C, TAP1, and TAP2), dendritic cells (BATF3), macrophages (CD68 and IL1A), type-I anti-tumor responses (CD8A and GZMB), and cell proliferation (MKI67) in 178 PAAD tissues." (PMID 35720314, 2022). "Interestingly, blocking only CXCR3 led to a loss of tumor control through this combination therapy, underpinning the importance of Batf3 DCs and CXCR3 ligands for the recruitment of CTLs and tumor killing." (PMID 35626062, 2022). "SETDB1 could also inhibit T cell cytotoxicity and promote tumor growth and immune cell infiltration via the FOSB/miR-22/BATF3/PD-L1 axis." (PMID 35497876, 2022). "Furthermore, SETDB1 silencing promoted the T cell-mediated cytotoxicity to tumor cells via the FOSB/miR-22/BATF3/PD-L1 axis and hindered CRC tumor growth in mice while leading to decreased immune cell infiltration." (PMID 35497876, 2022). "Repeated radiations at doses (8 Gyx3) above the threshold of Trex1 induction greatly amplified type-1 IFN production, resulting in recruitment and activation of Batf3-dependent dendritic cells, which are essential for priming of CD8+ T cells that induce tumor rejection in the context of ICI." (PMID 36077606, 2022). "Of note, Batf3 KO mice treated with Alb-IFNβ still were able to control tumor growth compared with untreated mice were, suggesting that although Batf3 alone is important for Alb-IFNβ effect it is not the only contributing factor." (PMID 35459734, 2022).